E2F1 (E2F transcription factor 1)
Diseases named in the same sentence as E2F1 in open-access papers (continued):
Sharing a sentence is not in itself a finding about the gene and the disease.
cancer (continued). "Expression of the E2F1 gene, one of eight E2F family genes, is induced at the G1/S boundary of the cell cycle, by E2F itself, resulting in high E2F1 promoter activity in a wide variety of cancers." (PMID 41439972, 2025). "Indeed, the ARF promoter exhibited higher cancer cell specificity than the E2F1 promoter in driving a suicide gene expression." (PMID 41439972, 2025). "E2F1-dependent apoptosis may also be induced for cancer therapy by activating E2F1 beyond the threshold required for apoptosis." (PMID 40517236, 2025). "Thus, our data provide evidence that the E2F1-HMGCR axis plays a central role in controlling the ferroptosis resistance of immune-refractory cancer." (PMID 41339438, 2025). "Previous studies also suggested cross-talk between E2F1 and condensin subunits in other cancers." (PMID 41319185, 2025). "Thus, E2F1 controls both cell cycle progression and ribosome biogenesis, making constitutive activation of E2F1 an attractive strategy for cancers to promote growth." (PMID 40517236, 2025). "E2F1 also serves as a TF that plays an important role in cancer progression." (PMID 39368995, 2024). "Notably, 17 TFs among the X-linked male-amplifiers exhibited motif enrichment across more than two cancer types, including AP-1, E2F1, and Sox7." (PMID 39716176, 2024). "E2F1 regulates a variety of cancers at the transcriptional level." (PMID 38783241, 2024). "E2F1 is a driver oncogene involved in the occurrence and development of malignant tumours." (PMID 38378679, 2024). "TRIM28 operates in inhibiting E2F transcription factor 1 (E2F1) and may act as a partial backup mechanism to impede E2F1‐induced apoptosis in cancer cells." (PMID 39534556, 2024). "In addition, the single and double knockdown simulations of the GRN identified E2F1 as one of the top TFs whose knockdown significantly increased the cancer state, which is supported by the survival analysis of the AML patients." (PMID 38594351, 2024). "Thus, enhancement of deregulated E2F1 activity in cancer cells is expected to contribute to cancer treatment." (PMID 39595534, 2024). "A master player in the E2F1-induced cancer-immune cell crosstalk is IL-6." (PMID 39544930, 2024). "In addition to influencing malignant transformation, E2F1 significantly regulates therapeutic response to cancer cells." (PMID 39119602, 2024). "When E2F1-mediated gene repression occurs, cancer cells will undergo apoptosis." (PMID 38783241, 2024). "Based on these facts, blocking E2F1-lncRNA interaction may provide a potential therapeutic approach for tackling cancer." (PMID 39119602, 2024). "In addition, E2F1 contributes to the manifestation of cancer stem cells, linking E2F-dependent processes with immune cell crosstalk in cancer progression." (PMID 39544930, 2024). "For this, we performed RBL2 and E2F1 ChIP in RBL2-LOH cancer CSCs." (PMID 38678032, 2024). "The molecular mechanisms of lncRNA/E2F1 crosstalk in human cancers." (PMID 39119602, 2024). "Another study revealed that PRR11 could promote cell proliferation by regulating PTTG1 through interaction with the transcription factor E2F1 in the pan-cancer setting." (PMID 38427643, 2024).
cancer (continued). "Cancer-promoting effect of E2F1 was reported in gallbladder cancer and gastric cancer." (PMID 38783241, 2024). "In CRC, miR-326 has ability to impede cancer growth by directly inhibiting E2F1." (PMID 37587156, 2023). "E2F1 could be served as a prognostic biomarker in cancer patients and higher levels of in cancer patients could predict shorter overall survival and disease-free survival." (PMID 37277745, 2023). "Indeed, the ARF promoter, which is specifically activated by deregulated E2F, showed higher cancer-cell specific activity, compared to the E2F1 promoter, which is also activated by E2F induced by growth stimulation." (PMID 36833320, 2023). "This SETD6-mediated methylation of E2F1 may have implications for the progression of diseases, including cancer." (PMID 37690684, 2023). "Thus, increasing deregulated E2F1 activity in cancer cells represents a novel, cancer-specific therapeutic approach." (PMID 36833320, 2023). "PubMed, Web of Science and CNKI database were searched until May 31th, 2022 by using key words to retrieve the published essays on the role of E2F1 expression in the prognostic value of cancer." (PMID 37277745, 2023). "In most cancer cells, elevated E2F1 drives uncontrolled proliferation." (PMID 36778475, 2023). "Enhanced E2F activity in cancer cells has been utilized to express cytotoxic genes (suicide gene therapy) or viral genes essential for the replication of viruses (oncolytic virotherapy) by utilizing growth-related E2F targets, such as the E2F1 promoter." (PMID 38132337, 2023). "E2F1 target pathways are considered as important targets for cancer treatment." (PMID 37538797, 2023). "In spite of this, cancer cells survive with deregulated E2F activity, implying that deregulated E2F1 activity may be suppressed by yet unknown factors." (PMID 36833320, 2023). "Therefore, more detailed study designs and follow-up are still needed to explore the prognostic value of E2F1 in cancer patients." (PMID 37277745, 2023). "In short, our study concluded that E2F1 can be used as a prognostic marker for cancers." (PMID 37277745, 2023). "The pooled results showed that higher E2F1 expression was significantly correlated with unfavorable overall survival (HR = 1.10, I2 = 95.3%, *PHeterogeneity = 0.000) and disease-free survival (HR = 1.41, I2 = 95.2%, *PHeterogeneity = 0.000) of cancer patients." (PMID 37277745, 2023). "In addition, the oncogenic role of E2F1 in mediating cancer chemoresistance has been confirmed by multiple previous studies." (PMID 36720923, 2023). "E2F1 in our top list is a well-recognized regulator of the cell cycle and a potent mediator of DNA-damage-induced apoptosis and checkpoint response and has been reported to play an important role in promoting various cancers." (PMID 37175660, 2023). "E2F1 has been confirmed to be highly expressed in a variety of cancers." (PMID 37277745, 2023). "However, the ARF promoter showed comparable activity to the E2F1 promoter in cancer cells, thereby showing higher cancer cell specificity than the E2F1 promoter." (PMID 38132337, 2023). "In the past, E2F1 was characterized by its pro-apoptotic activity in many types of human cancers." (PMID 36034466, 2022). "Therefore, this study revealed that NRF1 promotes cancer cell growth via the indirect transcriptional activation of E2F1 and is a potential biomarker in LIHC." (PMID 35448958, 2022).
cancer (continued). "Furthermore, the MTA3 expression levels were correlated with cancer hallmarks, including the G2/M checkpoint, E2F1 targets, and MYC targets." (PMID 36050478, 2022). "E2F1 can modulate the proliferation and invasiveness of multiple types of cancers." (PMID 35030974, 2022). "In addition, CDK2 overexpression significantly attenuated the anti-cancer effect of erdafitinib by affecting the transcriptional activity and expression of E2F1, as well as the expression of CDK1." (PMID 36235266, 2022). "Similarly, G9a enhances myoblast proliferation by enhancing E2F1 target gene expression and is upregulated in many cancers." (PMID 36158208, 2022). "E2F1 has contradictory roles in cancer, and its function has been under debate for years." (PMID 35448958, 2022). "This is consistent with the previously reported role of E2F1 in cancers." (PMID 35911954, 2022). "Under the same conditions, the Caspase-3 activity has been improved by VA, which indicates that E2F1/E2F3/Caspase-3 axis may be one of the anti-cancer mechanism of VA." (PMID 36175803, 2022). "E2F1 is a critical transcription factor highly expressed in most cancer tissues." (PMID 36221072, 2022). "To understand the extent that the changes in TLS gene expression could be attributed to increased E2F1 availability, we performed an in silico screen of RNAseq data from 1020 cell lines in the cancer cell line encyclopedia." (PMID 36266721, 2022). "It was suggested that the regulatory network of KAT2A and E2F1 involved in the cancer process was very complex, and it could regulate the expression level of genes involved in the cancer development process." (PMID 36292703, 2022). "The RB/E2F1 pathway is a master regulator of cancer cell metabolism in advanced disease." (PMID 35383175, 2022). "The loss control of the cell cycle induced by upregulated E2F1 in the HPV-positive group of CESC, HNSC, and UCEC and downregulated RB1 in the HPV-positive group of STAD played an important role on the formation and progression of the four cancers." (PMID 35392231, 2022). "E2F1 has been found to be deregulated in many types of cancers." (PMID 35689245, 2022). "E2F1 transcription factor was a key regulator of genes required for cell cycle progression, cell proliferation, and differentiation, and played a key regulatory role in the invasion–metastasis cascade of certain cancer types." (PMID 36292703, 2022). "E2F1, a key transcription factor, mediates the expression of various genes involved in fundamental cellular functions mainly related to cell growth and proliferation is hyperactive in most human cancers including LUAD and LUSC34–37." (PMID 35169159, 2022). "It is widely known that E2F1 is involved in both cancer cell growth and apoptosis." (PMID 36316351, 2022). "The transcription factor E2F1 plays an important role in the regulation of critical cellular processes, including cell cycle arrest and apoptosis, which makes it the object of intensive research in the context of cancer prevention and treatment." (PMID 35457270, 2022). "Besides, chemotherapeutic drugs promoted a positive feedback loop via ATM/E2F1 (E2F transcription factor 1)/STAT signaling that boosted the TRIM37 network in chemoresistant cancer cells." (PMID 35163586, 2022). "Overexpression of NF-YB could impact cancer cells, as this subunit was shown to have a pro-survival effect, in partnership with E2F1." (PMID 34208636, 2021). "Therefore, E2F1 plays a conflicting role in cancer, which is highly dependent on the cellular context." (PMID 33986804, 2021). "E2F1 has been reported as an oncogene, and its downregulation by miRNAs has been suggested to reduce malignant behaviors, such as proliferation, invasiveness, and resistance to apoptosis of cancer cells." (PMID 34758200, 2021). "Previous studies have reported that E2F1 mediates carcinogenesis in various cancers." (PMID 34335934, 2021). "Pan-cancer analysis of E2F1 revealed that E2F1 was commonly overexpressed in cancerous tissues." (PMID 34699320, 2021).
cancer (continued). "We validated these findings using publicly available scRNAseq data and found that cancer cells expressing Ki-67 and E2F1 overlapped and the percentage of cancer cells expressing Ki-67 varied among the 23 patients and correlated with the percentage of cancer cells expressing E2F1." (PMID 34256801, 2021). "Furthermore, both E2F1 and its seven target genes were overexpressed in primary tumors of patients with recurrent cancer." (PMID 33852600, 2021). "The E2F1 transcription factor is responsible for the regulation of proliferation and apoptosis and plays a role in DNA repair; it is deregulated in many types of cancers." (PMID 33799504, 2021). "MiR-1205 serves as a cancer suppressor by disengaging the interplay of MDM4/E2F1 and KRAS in NSCLC." (PMID 33589572, 2021). "Many studies have confirmed the cancer-promoting effect of E2F1." (PMID 34499617, 2021). "We hypothesized that E2F1 might transcriptionally induce the RBPs other than ESRP1 to support hypoxic adjustments to the cancer spliceome." (PMID 34362878, 2021). "Abnormalities in E2F1 gene expression are found in several human cancers." (PMID 33883577, 2021). "These may modulate myb which in turn may downregulate the E2F1 transcriptional factor involved in creating a ‘second wave of transcription’ for progressing through aberrant cell cycle during cancer." (PMID 33980898, 2021). "Our results identified transcriptional activation of PLANE as a mechanism involved in E2F1 promotion of cell proliferation, suggesting that PLANE may represent a potential target for counteracting the cancer-promoting axis of E2F1 signalling." (PMID 34145290, 2021). "Activation of E2F1 can also initiate the target genes transcription to maintain the progression of the cell cycles and induce the progression of anti-apoptosis and cell invasion in cancers." (PMID 34079762, 2021). "Hopefully, the discovery of chemicals such as small-molecule drugs and miRNAs that especially target E2F1 may be an effective treatment strategy for cancer therapy." (PMID 34650921, 2021). "In our previous study on E2F1-driven transactivation of downstream targets and its function in cancer cells, we have shown that inhibitor of β-catenin and TCF4 (ICAT), also known as the β-catenin interacting protein 1 (CTNNBIP1), is a direct transcriptional target of E2F1." (PMID 32326181, 2020). "Among them, E2F1 was previously confirmed to be a transcription factor in cancers." (PMID 32351327, 2020). "Former study revealed that E2F1 could promote cancer progression through transcriptionally activating some genes." (PMID 31934717, 2020). "In general, high levels of PRMT5 and E2F1 occurred in a range of cancers." (PMID 32709847, 2020). "In particular, microRNA-16-5p modulates Cyclin D1/E1-pRb-E2F1 pathway in cancer cells." (PMID 31900225, 2020). "Importantly, the VNTR harbors a binding site for the transcription factor E2F1, which shows enhanced binding ability in the VNTR genotypes associated with different forms of cancer." (PMID 31935919, 2020). "Dysregulation of E2F1 has been demonstrated in a number of cancers, including lung cancer." (PMID 31934717, 2020). "Abnormal expression and gene amplification of E2F1 has been observed in many types of human cancer." (PMID 33261027, 2020).
cancer (continued). "Thus, in cancer the dysregulation of E2F1 and/or Ras results in an auto-amplification loop which promotes proliferation and facilitates cancer transformation." (PMID 33665206, 2020). "To further verify whether circ_0088233 as a ceRNA of miR-185-3p, we investigated its effect on the level of circ_0088233 knockdown on the levels of WNT2B and E2F1, which are the targets of miR-185-3p identified in cancer cells." (PMID 33195183, 2020). "E2F1 transcription factor functioned as a key regulator of cancer progression, including BRCA." (PMID 33102693, 2020). "Furthermore, E2F1 is reported to be overexpressed in specific cancer cells compared with its expression in normal cells, and the upregulation of E2F1 has been associated with poor prognosis." (PMID 31534120, 2019). "However, while E2F1 constitutes the “final frontier” of the G1-to-S phase boundary that preserves cellular homeostasis, this factor switches duties during cancer progression and is engaged to pathways favoring invasiveness, therapy resistance, and metastasis." (PMID 31287003, 2019). "It has recently been reported that the ATR/Chk1 pathway plays a key role in promoting RRM2 accumulation by stabilizing E2F1 in the S-phase cells, which may be important for countering the replication stress in cancer cells." (PMID 31324785, 2019). "Several oncogenes inactivate Rb and loss of the E2F1 negative feedback system allows the uncontrolled proliferation of cancer cells." (PMID 31142321, 2019). "Although these results suggest that E2F1 is a dependable marker for multiple cancer types, its expression level within these cancers, specific biological function and molecular mechanism of action remain mostly unknown." (PMID 31534120, 2019). "Puzzlingly, most cancer cells show high levels of E2F1, which is supposed to repair damaged DNA." (PMID 31534120, 2019). "E2F-1 transgenic mice develop cancers in the vagina, skin, forestomach, and odontogenic epithelium." (PMID 30970566, 2019). "In addition, GBA attenuates the evolution of cancer cell resistance to gemcitabine by inhibiting ERK/E2F1/RRM2 signaling pathway." (PMID 31878360, 2019). "The overexpression and gene amplification of E2F-1 in a variety of cancers are reported." (PMID 30970566, 2019). "Consistent with the crucial roles that Sp1 and E2F1 play in the modulation of miR-203 transcription, overexpression of E2F1 in T24T(shXIAP) cells markedly increased the cancer cell invasion, while knockdown of Sp1 in T24T cells significantly inhibited the cancer cell invasion." (PMID 31811115, 2019). "Altogether, these data suggest E2F1 as a potential therapeutic target for cancer cells." (PMID 29743521, 2018). "Alteration of cIAP1 could be a supplementary event that culminates in the dysregulation of the E2F1/Rb axis in cancer." (PMID 30359437, 2018). "We showed that in E7‐expressing cells, GCN5 regulated E2F1 expression that is accompanied by elevated level of histone 3 lysine 9 acetylation in the promoter of E2F1, is a novel observation for a potential role of GCN5 in HPV‐associated cancers." (PMID 30079588, 2018). "Moreover, in 24-hours IHC assay the expression of Mad1 and E2F1 was, respectively, six and two folds higher in the mono system-treated cancer mice compared to the healthy ones." (PMID 29938000, 2018). "The ANRIL promoter was also responsive to E2F1 in cancer cells." (PMID 30087655, 2018). "Furthermore, we show that Rad52 was upregulated transcriptionally in a manner dependent on E2F1, a transcription factor that also drives G1/S transition and which is frequently overexpressed in cancer." (PMID 29548335, 2018).